IL1B (interleukin 1 beta)
Diseases named in the same sentence as IL1B in open-access papers (continued):
Sharing a sentence is not in itself a finding about the gene and the disease.
liver disease (77 papers, 2013 to 2025). "Inflammation and elevated cytokines such as TNF-α and IL-1β are known to follow hepatocellular injury and are associated with the pathogenesis of liver diseases, in part, through the activation of the NF-κB signaling pathway." (PMID 37108064, 2023). "NFKBIA mutations promote the formation of IL-1β, and give rise to severe immune deficiency in liver diseases." (PMID 37056763, 2023). "Induction of inflammation has been implicated in IR-mediated hepatic disease, which was confirmed by the upregulated gene expression levels of Bax and IL-1β as well as upregulated protein expression levels of TNF-α and IL-6 in the vehicle-treated IR rats." (PMID 36655319, 2023). "Among the well-recognized mediators, TNF-α, IL-6, and Il1β have been implicated in the regulation of inflammation in liver diseases." (PMID 36588728, 2022). "Increasing clinical and experimental studies have demonstrated that inflammasome activation-dependent IL-1β is a major cause and contributes to liver disease progression." (PMID 36160411, 2022). "The activation of the NLRP3 inflammasome and the release of downstream IL-1β and IL-18 have been shown to be associated with the pathogenesis of various liver diseases." (PMID 30105078, 2018). "Activation of the inflammasome and the subsequent production of IL-1β are implicated in many models of liver inflammatory disease." (PMID 25847140, 2015). "Acetaminophen-induced hepatotoxicity is dependent on the activation of the inflammasome, and IL-1β production via activation of the inflammasome is also pivotal in hepatitis C virus infection-associated hepatic disease." (PMID 25847140, 2015). "This relationship is further evident by our RNA-seq analysis, which revealed that IL-1β and IL-1β-driven genes are associated with severe liver disease." (PMID 23633957, 2013). "Our observations define the hepatic macrophage/HCV interface and IL-1β production through the NLRP3 inflammasome as critical features underlying liver disease in chronic HCV infection." (PMID 23633957, 2013). "The linkage of these processes of innate immune evasion/persistent viral replication and viremia/IL-1β production and response thus mediates a cycle of chronic inflammatory stimulation that underlies liver disease in HCV infection." (PMID 23633957, 2013). "IL1B is a key inflammatory cytokine to mediate alcohol-associated liver disease." (PMID 35336897, 2022). "Since IL-1α, IL-1β, IL-33, and IL-36 are implicated in vivo during liver diseases, the efficiency of the therapeutic approaches based on targeting a cytokine by the other members may be affected." (PMID 31507607, 2019). "As reported by C. D’Melloand M.G. Swain (2011), cytokines TNF, IL-1β, and IL-6 arelikely to be key promoters of central neural alterations inchronic liver diseases." (PMID 40144377, 2025). "An imbalance of cytokines, namely Interleukin-1β (IL-1β), IL-6, and IL-10, can lead to liver diseases, including fibrosis and acute inflammation." (PMID 40584441, 2025). "Blocking the molecules involved in the pyroptosis pathway (such as NLRP3 and IL-1β) can affect the onset and progression of liver disease, providing potential therapeutic targets for liver disease." (PMID 39917567, 2025). "Given the close relationship between NLRP3 inflammasome, IL-1β, and IL-18 and their pivotal roles in the progression of liver diseases through the recruitment of inflammatory cells, we assessed the expression of NLRP3 inflammasome." (PMID 39949920, 2025). "Here, we have found that a high level of TNF-α and IL1β in the serum of chronic alcoholic with either -238GA or -31CT genotype correlated well with their liver disease status." (PMID 38146363, 2023). "On the other hand up-regulation of the release of TNF-α and interleukin-1 beta (IL-1β) by Kupffer cells and stimulated hepatic stellate cells (HSCs) exhibit liver disorder." (PMID 37427328, 2023).
liver disease (continued). "Among them, IL-1β plays a crucial role in liver diseases, being involved in all essential stages, from liver inflammation to liver fibrosis." (PMID 38004466, 2023). "TNF-α, IL-1β, IL-6, and IL-18 are often used as markers of inflammatory responses and are involved in the induction of liver diseases." (PMID 36865438, 2023). "IL-1β exerts a pro-inflammatory role in liver disease by interacting with IL-1R and the expression is low in the healthy liver." (PMID 35268138, 2022). "Historically, inflammasomes are central to regulating liver diseases, which has been attributed to their ability to induce hepatic inflammation by up-regulating the expression of IL-1β/IL-18." (PMID 36160411, 2022). "In Gr.2, IL-6 and MCP-1 were numerically high, and IL-8 and IL-1β were lower, suggesting immunological uniqueness by the staging of the liver disease." (PMID 36232646, 2022). "In the liver, studies have revealed that C. albicans overgrowth promotes damage to hepatocytes and the development of ethanol-induced liver disease through increased IL-1β expression and secretion." (PMID 35369462, 2022). "Serum IL-1RA concentration was negatively correlated with the end-stage liver disease score model, IL-1RA concentration, and IL-1RA/IL-1β ratio of HBV-ACLF patients in the death group was pronouncedly lower than those in the survival group." (PMID 36117587, 2022). "Alcohol can induce the increase of endotoxin level, activate Kupffer cells, and trigger the excessive production of TNF-α, IL-1β, and IL-6, which participate in the pathogenesis of liver diseases." (PMID 35409071, 2022). "Interleukin-1 beta (IL-1β) promotes liver disease progression and hepatocarcinogenesis in chronic hepatitis B (CHB)." (PMID 36678401, 2022). "IL-1β activation is triggered by various danger signals, including MAMPs, and is an important player in a number of inflammatory liver diseases." (PMID 34556145, 2021). "As an important inflammatory factor, IL-1β plays an important role in mediating inflammatory response in a variety of liver disease models." (PMID 34366873, 2021). "From the perspective of liver disease such as non-alcoholic steatohepatitis, the inflammatory cytokines (IL-1β, IL-2, and TNF-α) are produced in the liver and are associated with disease (Bruscalupi, Agostinelli, Stronati & Cucchiara, 2015)." (PMID 34917853, 2021). "Considerable evidence supports that TNF-α and IL-1β are related to liver diseases’ pathogenesis by activating the NF-κB signaling pathway." (PMID 33671028, 2021). "Inflammasome triggers or amplify liver diseases by releasing pro-inflammatory cytokines such as IL-1β, IL-1α, IL-18, and also through other inflammatory mediators such as High Mobility Group Box 1 (HMGB1)." (PMID 32431709, 2020). "In liver disease, IL-1β promotes the recruitment of inflammatory cells to the liver and induces TG accumulation in hepatocytes." (PMID 32903542, 2020). "IL-1β is a key pro-inflammatory cytokine that plays a promising role in the progression of several liver diseases." (PMID 30022981, 2018). "The overexpression of TNF-α and IL-1β was found to be enhanced in both animal models and patients with liver disease." (PMID 28387740, 2017). "Many studies also demonstrated that IL-1b and TNF-α play a key role in the development and maintenance of inflammatory and those cytokines' elevation is associated with many liver diseases." (PMID 26881046, 2016). "Understanding how such crosstalk imparts restriction of HCV infection and effective antiviral immune responses should reveal novel IFN/IL-1β interactions that balance liver inflammation and immune actions for the control of liver disease." (PMID 23633957, 2013). "The results showed that hepatic Il‐1b was significantly increased in mice in the FR15%–Re group, which was alleviated by FMT treatment, that is, high‐fat Re after a moderate dietary restriction has the potential to cause the development of liver disease." (PMID 39021516, 2024).
liver disease (continued). "In liver disease, innate immune cells respond to hepatic insults by activating cell-intrinsic inflammasomes via toll-like receptors and NF-κB, and by releasing pro-inflammatory cytokines (such as IL-1β, IL-18, TNF-α and IL-6)." (PMID 38908436, 2024). "The negative correlation with key inflammatory cytokines, notably those involved in acute and chronic inflammatory responses and liver diseases, like IL-1β, IL-18, and TNF-α, reinforces the hypothesis that CR1L might have a protective role in AH." (PMID 38573776, 2024). "In the context of liver diseases, cytokines have been assigned fundamental properties reflecting common function, including proinflammatory cytokines (e.g. IL‐1α, IL‐1β, TNF‐α, and IL‐2), immunoregulatory cytokines (e.g. IFN-γ), and anti-inflammatory cytokines (e.g. IL-10 and IL-4)." (PMID 33841403, 2021). "Inflammatory mediators including TNF-α, IL-1β, and IL-10 may influence the progression of liver disease." (PMID 33117360, 2020). "Although the role of some members of the IL-1 cytokine family in liver disease has been extensively studied (IL-1α, IL-1β, IL-33), leading to strong arguments favoring these molecules as potential therapeutic targets, the role of the other members (IL-36, IL-37, IL-38) remains to be elucidated." (PMID 31507607, 2019). "We have tried to apply the concept of trained immunity to liver diseases, based on the role of the members of the IL-1 superfamily, first of all IL-1β but also IL-18 and IL-33, in modulating innate lymphoid immunity carried by natural killer cells, innate lymphoid cells or innate T-αβ lymphocytes." (PMID 31507607, 2019). "NOD-like receptor protein 3 (NLRP3) inflammasome, a multiprotein complex, contributes to the development of liver disorders, such as alcoholic steatohepatitis, viral fulminant hepatitis, and non-alcoholic fatty liver disease, through processing caspase-1 cleavage and IL-1β secretion." (PMID 29692782, 2018). "In fact, IL-1β has recently come back under the spotlight in the field of liver disease." (PMID 27046197, 2016). "The fact that the IL-1 receptor antagonist anakinra markedly inhibited IL-1β’s effects on LX-2 cells suggests that this drug could be tested as an anti-inflammatory in patients with liver disease." (PMID 27046197, 2016). "Considerable evidence suggests that TNF-α and IL-1β contribute to the pathogenesis of liver inflammatory diseases by activating the NF-κB signaling pathway, suggesting that it may be important to monitor proinflammatory cytokines when studying liver injury." (PMID 26798422, 2016). "IL-1β is a pro-inflammatory cytokine involved in various liver diseases." (PMID 25551609, 2014). "Thus, IL-1β and IL-1β–responsive proinflammatory cytokine expression associates with HCV infection and liver disease severity." (PMID 23633957, 2013). "Importantly, expression of IL-1β, a key proinflammatory cytokine, generally associated with HCV infection and the onset of liver disease." (PMID 23633957, 2013). "Moreover, IL-1RA inhibits liver inflammation by blocking IL-1β and inflammasome pathways, which have been speculated to be the major drivers of various liver diseases." (PMID 38004466, 2023). "The MCD model shows a notable rise in pro-inflammatory cytokines like IL-1β and TNF-α in the intestines, suggesting a connection between gut inflammation and the advancement of liver disease." (PMID 41001122, 2025). "In liver diseases, signaling pathways such as TLR4 and NF-κB activate endogenous cellular inflammatory vesicles, releasing pro-inflammatory cytokines like IL-1β, IL-6, and TNF-α." (PMID 39936090, 2025). "IL-1β, TNF-α, and IP-10 post-HKEB stimulation and IP-10 post-LPS stimulation negatively correlated with biochemical markers of liver disease severity and liver disease severity scores." (PMID 35195033, 2022).
liver disease (continued). "In the early phase of liver diseases, Kupffer cell-derived proinflammatory cytokines, including CCL2, IL-1β, IL-6, IL-23, and TNF-α, induce the migration of immune cells and HSCs and contribute to the development of a proinflammatory liver microenvironment." (PMID 36380016, 2022). "Mitochondrial stress and lesions can promote cell death, liver fibrogenesis and inflammation in the development of liver diseases by NLRP3 inflammasome and IL-1β activation." (PMID 35365229, 2022). "Considerable evidence has accumulated to suggest that the NF-κB signaling pathway contributes to the pathogenesis of liver inflammatory diseases through the activation of TNF-α, IL-6, and IL-1β." (PMID 29849889, 2018). "Hepatic pyroptosis controls IL-1β production, which has been reported to promote the production of other proinflammatory cytokines (such as TNF-α and MCP-1) and aggravate the inflammatory response in liver disease." (PMID 38090607, 2023). "It has proposed that mature IL-1β secretion requires appropriate process by NLRP3 activation and caspase-1 cleavage in various liver diseases, including alcoholic steatohepatitis, viral fulminant hepatitis, non-alcoholic fatty liver disease, and heat stroke-induced liver injury." (PMID 29692782, 2018). "For instance, whereas a significant increase in the production of IL-1β, IL-6, IL-12, and TNFα was observed in chronic alcoholics without liver disease, chronic alcoholics with liver disease who were drinking alcohol showed low production of IL-1β and TNFα." (PMID 25762940, 2015). "It was reported that IL-1β protects mice from FasL-induced apoptosis, but negatively influenced liver disease." (PMID 25551609, 2014). "CXE is proven to suppress NO, pro-inflammatory (IL-6, IL-1β, and LDH), and apoptosis genes (Casp-9, Casp-3, and JNK) in APAP-mediated liver cells while increasing the expression of an anti-inflammatory agent (IL-10), which can be a potent target for liver disease treatment." (PMID 40584441, 2025). "In addition, it has been shown to have a hepatoprotective effect against the toxicity of paracetamol and acetaminophen, with the treatment of liver diseases achieved through inhibition of cyclooxygenase-II, TNF-α, interleukin-1-beta (IL-1-β), and inducible nitric oxide synthase (iNOS)." (PMID 39502378, 2024). "PBC patients have been reported to have higher serum levels of gut endotoxins/lipopolysaccharide, with increased expression of toll-like receptor (TLR) 4 and pro-inflammatory cytokines TNF-α, IL-1β, IL-6, and IL-8 compared to non-PBC liver disease." (PMID 39859319, 2025).
hyperuricemia (76 papers, 2012 to 2026). An abnormally high level of uric acid. "Tear IL‐1β concentration was elevated in the hyperuricemia group, and significantly positively linked to tear uric acid level, implying an interaction between hyperuricemia and inflammation responses." (PMID 36988248, 2023). "The exact mechanism showing how uric acid mediates these co-morbidities is incompletely understood; however, it is becoming more evident that the sterile inflammation caused by hyperuricaemia via triggering of IL-1β production is a key process." (PMID 33748660, 2021). "A positive association was observed between tear IL‐1β and serum/tear uric acid levels, implying that elevated tear uric acid level may be involved in the development of eye inflammation related to hyperuricemia." (PMID 36988248, 2023). "Other studies have also found that TLRs/NF-κB signaling pathway and NLRP3 inflammatory body activation may lead to IL-1β–driven inflammatory response, causing hyperuricemia in kidney injury." (PMID 32089717, 2020). "Thus, IL‐1β concentration may be considered a potential indicator and treat target of hyperuricemia‐associated ocular disorders." (PMID 36988248, 2023). "Hyperuricemia promotes the release of proinflammatory cytokines such as IL-1β by activating the NLRP3 inflammasome, leading to atrial fibrosis and structural remodeling." (PMID 40469443, 2025). "IL‐1β concentrations were significantly higher in hyperuricemia eyes compared to control eyes (210.2 ± 113.9 vs." (PMID 36988248, 2023). "The results illustrated that tear IL‐1β level was significantly higher in hyperuricemia group than in healthy control group (210.2 ± 113.9 vs." (PMID 36988248, 2023). "There was a significant positive correlation between tear uric acid value and tear IL‐1β level, implying an interaction between hyperuricemia and ocular inflammation responses." (PMID 36988248, 2023). "The levels of NLRP3 and IL-1β inflammatory factors in serum and kidney of hyperuricemia mice also increased significantly." (PMID 36120294, 2022). "Increases in IL-1β expression were observed in the serum and kidney tissues of PO-induced hyperuricemia rats (p < 0.05 and p < 0.01, respectively)." (PMID 35726318, 2022). "We detected the serum IL-1β levels in the high-purine diet and potassium oxonate-induced hyperuricemia rats." (PMID 36245501, 2022). "Network pharmacology and untargeted metabolomics indicated that ten yellow tea bioactive ingredients and 35 targets were responsible for preventing hyperuricaemia, which was mediated by 94 signalling pathways, including IL-1β and TNF." (PMID 36109783, 2022). "White tea and green tea slightly reduced it, while yellow tea significantly reduced the level of IL-1β in the serum of rats with hyperuricaemia." (PMID 36109783, 2022). "When the XOD inhibitor is given for uric acid-lowering treatment, a significant decrease in serum IL-1β levels in patients with hyperuricemia can be observed." (PMID 36569836, 2022). "In another investigation, the NLRP3, ASC, caspase-1 gene and protein expression in PBMCs, and the IL-1β and IL-18 protein concentrations in plasma of patients with hyperuricemia and patients with UAN were significantly higher compared to healthy controls." (PMID 35204131, 2022). "Although IL-1β has a known critical role in gout, increasing evidence suggests that other IL-1 family members are also involved in the pathogenesis of hyperuricemia and gout flares." (PMID 36203589, 2022). "The results showed that compared to those in the healthy control group, the serum inflammatory cytokine levels of IL‐1β and IL‐18 in hyperuricaemia patients were significantly higher." (PMID 34296520, 2021). "In this study, we demonstrated that hyperuricemia can cause intrarenal crystal formation in the kidney, macrophage infiltration, and upregulation of NLRP3 and IL-1β expression." (PMID 33648977, 2021).